FGL1 (fibrinogen like 1)
Diseases named in the same sentence as FGL1 in open-access papers (continued):
Sharing a sentence is not in itself a finding about the gene and the disease.
rheumatoid arthritis (7 papers, 2020 to 2024). A chronic, systemic autoimmune disorder characterized by inflammation in the synovial membranes and articular surfaces. "Elevated FGL1 expression is positively correlated with the severity of acute pancreatitis, the disease activity of rheumatoid arthritis, and the severity of radiation-induced acute liver injury." (PMID 37153794, 2023). "Protein omics suggest that FGL1 acts as a biomarker for predicting rheumatoid arthritis progression and could be used for evaluating the pathogenesis of Crohn’s disease." (PMID 36556955, 2022). "First, the value of FGL1 can predict the activity of rheumatoid arthritis (RA; moderate/high: 91.46%; remission/low: 80.77%) and the severity of dengue fever." (PMID 34526102, 2021). "However, whether FGL1 has therapeutic potential for use in the T cell-induced the autoimmune disease, rheumatoid arthritis (RA), is still unknown." (PMID 34975855, 2021).
Hepatic steatosis (6 papers, 2013 to 2025). Steatosis is a term used to denote lipid accumulation within hepatocytes. "Hepassocin (also known as hepatocyte-derived fibrinogen related protein or fibrinogen-like 1) is a novel hepatokine that causes hepatic steatosis and induces insulin resistance." (PMID 33390768, 2021). "Our previous work in adolescents with hepatic steatosis also detected EV-derived proteins involved in complement activation and lipid metabolism, several of which exhibit high hepatic expression (e.g., FGL1, RBP4, GC)." (PMID 41354933, 2025). "The pathogenesis of MASLD alters the secretion of hepatokines such as fibrinogen‐like 1 (FGL1), a candidate mediator of liver steatosis and hyperglycemia." (PMID 40832769, 2025). "Fgl1 silencing using RNA interference was protective against high fat diet induced liver injury whereas the overexpression of Fgl1 was sufficient to induce hepatic steatosis." (PMID 40832769, 2025).
Hyperglycemia (5 papers, 2013 to 2025). An increased concentration of glucose in the blood. "Mice deficient of Fgl1 have fasting hyperglycemia, similar insulin sensitivity and enhanced gluconeogenesis." (PMID 23483972, 2013). "Consistently, a study of Fgl1-deficient mice showed global metabolic disorders, namely FGL1-null mice were heavier, had abnormal plasma lipid profiles, fasting hyperglycemia with enhanced gluconeogenesis, and exhibited differences in white and BAT morphology regarding wild types." (PMID 36011329, 2022). "Under stimulation by metabolic factors (hyperglycemia, hyperlipidemia, hormones, etc.), the liver secretes FGL1 and participates in the blood circulation." (PMID 34526102, 2021). "FGL1 null mice exhibited fasting hyperglycemia and enhanced hepatic glucose production." (PMID 34975333, 2022). "Thus the hyperglycemia in the Fgl1 null mouse likely occurs as a result of increased hepatic production and decreased uptake into adipose tissues." (PMID 23483972, 2013). "We generated an Fgl1 knock out mouse and find that it is larger than age matched wild type control mice, exhibits fasting hyperglycemia, changes in lipid metabolism, structural defects in brown and white adipose tissues and impaired expression of brown and white fat genes." (PMID 23483972, 2013).
non-alcoholic fatty liver disease (5 papers, 2019 to 2024). "Additionally, it is known that FGL1 has a role in developing non-alcoholic fatty liver disease although studies highlight that FGL1 has liver-protective effects against injuries." (PMID 35682868, 2022).
Autoimmunity (4 papers, 2020 to 2026). The occurrence of an immune reaction against the organism's own cells or tissues. "These evidences verify the function of FGL1 regulating autoimmunity and immune homeostasis via binding to lymphocyte-activation gene 3 (LAG-3) to inhibit T cell activation." (PMID 37153794, 2023). "Targeting FGL1 has shown preclinical efficacy in enhancing immunotherapy involving programmed death ligand 1 (PD-L1)/PD-1 checkpoint blockade, inhibiting liver metastasis and relieving autoimmunity without overt hepatotoxicity." (PMID 41789095, 2026). "However, mice harboring the LAG3 K27E mutation, which abolishes FGL1 binding without affecting MHC binding, did not experience exacerbation of T1D, implying that FGL1 is not required for LAG3-mediated mitigation of autoimmunity, at least in the NOD model." (PMID 38556085, 2024). "It is possible, for example, that the LAG3 K27E mutation tested in NOD mice did not completely abrogate LAG3–FGL1 interactions under physiological conditions in vivo and that FGL1 may still contribute to limiting autoimmunity." (PMID 38556085, 2024).
cervical cancer (4 papers, 2023 to 2025). A primary or metastatic malignant neoplasm involving the cervix. "Recently, tRF-Glu49 expression was found to be significantly downregulated in cervical cancer, and studies have shown that tRF-Glu49 inhibits cervical cancer proliferation, migration, and invasion by targeting fibrinogen-like protein 1(FGL1)." (PMID 37480078, 2023).
liver diseases (4 papers, 2020 to 2025). "To investigate the contribution of FGL1 to liver diseases, we compared wild‐type mice to mice with hepatocyte‐specific deletion of Fgl1 subjected to a steatosis or HCC experimental protocol." (PMID 40832769, 2025). "Two additional studies described a similar bi‐phasic regulation of Fgl1 transcription during liver diseases." (PMID 40832769, 2025). "Here, we provide a comprehensive review of the cellular mechanisms and clinical prospects of FGL1 in the prevention and treatment of liver diseases, metabolic disorders and cancer, and proffer suggestions for future studies." (PMID 34975333, 2022). "We discuss here, the role of FGL1 in liver diseases, metabolic disorders and cancer." (PMID 34975333, 2022). "This review provides an overview of the current knowledge regarding the roles of FGL1 and FGL2 in liver disease." (PMID 38816776, 2024). "Recent studies have highlighted the involvement of fibrinogen-like proteins, specifically fibrinogen-like protein 1 (FGL1) and fibrinogen-like protein 2 (FGL2), in the regulation of various liver diseases." (PMID 38816776, 2024). "Recent research has highlighted the involvement of fibrinogen-like protein 1 (FGL1) and fibrinogen-like protein 2 (FGL2), both members of the FREPs family, in the regulation of various liver diseases." (PMID 38816776, 2024). "The levels of fibrinogens (e.g., FGL1 and FGG) are increased in most patients with severe liver disease." (PMID 31998436, 2020). "Additionally, we discuss the potential of FGL1 and FGL2 as immunotherapeutic targets for various liver diseases." (PMID 38816776, 2024). "Furthermore, it explores the potential benefits and challenges of targeting FGL1 and FGL2 for liver disease treatment and the prospects of fibrinogen-like proteins as biomarkers for liver disease, offering insights for future research in this field." (PMID 38816776, 2024).
metastatic melanoma (4 papers, 2023 to 2025). A melanoma that has spread from its primary site to another anatomic site. "Elevated FGL1 levels have been associated with poor responses to PD1/PD-L1 blockade therapies, particularly in cancers like non-small cell lung cancer (NSCLC) and metastatic melanoma." (PMID 40469297, 2025). "For instance, high plasma FGL1 levels are associated with worse OS in NSCLC and metastatic melanoma patients treated with anti-PD-1 mAbs15." (PMID 37872170, 2023).
pancreatic cancer (4 papers, 2021 to 2025). "EPA supplements could potentially inhibit or reduce ACC-1-involved lipogenesis and HPS/FGL1-mediated cell survival in KRAS-mutated pancreatic cancer cells." (PMID 33801246, 2021). "In pancreatic cancer, the downregulation of FGL1 following ETV4 knockdown could potentially enhance the efficacy of immunotherapy by reducing immune suppression and improving T-cell activation." (PMID 40469297, 2025). "Interestingly, our study found that knocking down ETV4 leads to an upregulation of FGL1 expression in RBE and SK-hep1 cells, while the opposite effect was observed in pancreatic cancer cells and tumors, where ETV4 knockdown resulted in the downregulation of FGL1 expression." (PMID 40469297, 2025). "Moreover, we further validated the existence of a correlation between ETV4 and Fibrinogen-like protein 1 (FGL1), a major ligand for the inhibitory receptor LAG3, in pancreatic cancer, suggesting that the ETV4-FGL1 axis may be a key player in tumor immune evasion." (PMID 40469297, 2025). "Further RT-qPCR analysis of mouse tumor tissues demonstrated that knockdown of the ETV4 gene resulted in reduced FGL1 expression and no significant changes in HAVCR2, consistent with the results observed in BxPC3 pancreatic cancer cells." (PMID 40469297, 2025).
type 2 diabetes (4 papers, 2021 to 2024). "In clinical practice, changes in the FGL1 expression level can be specifically observed in type 2 diabetes patients with non-alcoholic liver disease." (PMID 34526102, 2021).
esophageal squamous cell carcinoma (3 papers, 2023 to 2025). Esophageal squamous cell carcinoma (ESCC) is a type of esophageal carcinoma (EC) that can affect any part of the esophagus, but is usually located in the upper or middle third. "We further investigated the clinical relevance of FGL1 protein or plasma levels in gastrointestinal tumors, including CRC, GC and esophageal squamous cell carcinoma (ESCC)." (PMID 37872170, 2023).
lung fibrosis (3 papers, 2019 to 2023). "Immunofluorescence analysis using mouse fibrotic lung tissues suggested that fibrotic regions showed increased expressions of Gtse1 and Fgl1, indicating novel molecular signatures of gtse1and fgl1 for IR-induced lung fibrosis." (PMID 30406363, 2019). "A recent study reported that FGL1 as a molecular candidate for radiation-induced lung fibrosis suggesting the involvement of radiation epithelial to mesenchymal transition using L132 human pulmonary epithelial cells." (PMID 31489941, 2019). "Although further functional analyses are required to determine the roles of GTSE1 or FGL1 during development of lung fibrosis, our results might provide the information that is useful for understanding IR-induced lung fibrosis." (PMID 30406363, 2019).
psoriasis (3 papers, 2023 to 2024). An autoimmune condition characterized by red, well-delineated plaques with silvery scales that are usually on the extensor surfaces and scalp. "Furthermore, a negative correlation was observed between HDL cholesterol levels and FGL1, indicating a possible role of FGL1 in psoriasis forms associated with lipid metabolism disorders." (PMID 38399624, 2024). "FGL1, a 68-kD protein from the fibrinogen family, was found to be significantly lower in the serum of psoriasis patients than healthy controls." (PMID 37546687, 2023). "Despite this observation, PASI scores of patients with psoriasis remained positively correlated with serum FGL1 concentration." (PMID 37546687, 2023). "Additionally, the study highlighted that measuring serum FGL1 levels provides better results in assessing psoriasis severity compared to serum IL-17 levels." (PMID 38399624, 2024). "Nevertheless, a decreased level of FGL1 is detected in the serum of psoriasis patients." (PMID 37153794, 2023).
Arthritis (2 papers, 2021 to 2023). Inflammation of a joint. "Long-termly and systemic administration of FGL1 to arthritis model may increase the risk of unpredictable effect during treatment." (PMID 34975855, 2021). "Deficiency of FGL1 can induce spontaneous dermatitis in gene knockout mice, and supplement of FGL1 recombinant protein improves collagen-induced arthritis." (PMID 37153794, 2023). "In this study, we evaluated the therapeutic effect of Fgl1 on arthritis progression in a collagen-induced arthritis (CIA) mouse model." (PMID 34975855, 2021). "In this study, we attempted to evaluate the therapeutic potential of FGL1 protein on arthritis progression in a collagen-induced arthritis (CIA) mouse model." (PMID 34975855, 2021). "We further evaluated the therapeutic efficacy of Fgl1 protein to disease progression in the CIA mouse model through monitoring the arthritis score, histological score and the expression of inflammatory cytokines in inflamed foot tissue." (PMID 34975855, 2021). "Arthritis on day 42 was inhibited 22% and 62.5%, by 10 and 50 μg/kg of Fgl1, respectively, as compared with the normal saline-treated control group." (PMID 34975855, 2021). "Treatment with Fgl1 further attenuated local inflammation, cellular infiltration, bone deformation and clinical score of arthritis in a CIA mouse model with minimal adverse events." (PMID 34975855, 2021). "Intraperitoneal administration of Fgl1 protein can significantly decrease inflammatory cytokine level in local paw tissue, prevent joint inflammation, cellular infiltration and bone deformation and attenuate collagen-induced arthritis progression in vivo." (PMID 34975855, 2021). "Here, we attempted to evaluate the effect of FGL1 protein on arthritis progression." (PMID 34975855, 2021). "Intraperitoneal administration of Fgl1 protein significantly decreased the inflammatory cytokine level (i.e., IL-1β and IL-6) in local paw tissue, and prevented joint inflammation, cellular infiltration, bone deformation and attenuated collagen-induced arthritis progression in vivo." (PMID 34975855, 2021).
autoimmune disease (2 papers, 2021 to 2026). A disorder resulting from loss of function or tissue destruction of an organ or multiple organs, arising from humoral or cellular immune responses of the individual to their own tissue constituents. "Pathologically, FGL1 is frequently upregulated in various tumors and autoimmune diseases and is closely related to the occurrence and development of these diseases." (PMID 41789095, 2026). "In summary, this study evaluated the therapeutic efficacy of FGL1 protein on the autoimmune disease RA." (PMID 34975855, 2021). "We thus expect that FGL1 will be suitable to serve as a combinatory therapeutic agent with other potential inhibitory ligand drugs in autoimmune diseases." (PMID 34975855, 2021). "We believe that Fgl1 protein may serve as a potential therapeutic agent for RA or other T cell-mediated autoimmune disease therapy in the future." (PMID 34975855, 2021).
Cirrhosis (2 papers, 2020 to 2022). A chronic disorder of the liver in which liver tissue becomes scarred and is partially replaced by regenerative nodules and fibrotic tissue resulting in loss of liver function. "Positive FGL1 expression on tumor cells (FGL1 TC+) correlated with a less Cirrhosis pattern (P = 0.002) and FGL1 IC+ was more frequent in patients with age older than 50 (P = 0.008)." (PMID 32762721, 2020).
colitis (2 papers, 2023 to 2024). Inflammation of the colon. "The findings showed that XJS ameliorated TNBS-induced experimental colitis via suppression of ferroptosis positively regulated by the FGL1/NF-κB/STAT3 positive feedback loop." (PMID 37153794, 2023). "It is the strength of this study that the roles of overactivated NF-κB and STAT3 on inducing ferroptosis in IECs and elevated FGL1 on enhancing colitis are uncovered." (PMID 37153794, 2023). "Overall, XJS might alleviate experimental colitis via suppression of the FGL1/NF-κB/STAT3 positive feedback loop." (PMID 37153794, 2023). "In conclusion, XJS might restrain ferroptosis in IECs to ameliorate experimental colitis by inhibition of FGL1/NF-κB/STAT3 positive feedback loop." (PMID 37153794, 2023). "Results in the present study confirmed that XJS might mitigate CD-like experimental colitis through inhibiting ferroptosis in IECs via downregulation of FGL1/NF-κB/STAT3 positive feedback loop signals." (PMID 37153794, 2023). "We also recognize a limitation that the mechanisms of NF-κB and STAT3 on regulating the SLC7A11/GSH/GPX4 antioxidant axis and XJS targeting FGL1 to inhibit colitis are not verified in vitro, which will be conducted in a future study." (PMID 37153794, 2023).
head and neck cancer (2 papers, 2022 to 2025). A primary or metastatic malignant neoplasm affecting the head and neck. "It is worth mentioning that FGL1 has been reported to be downregulated in pancreatic, breast, liver, and head and neck cancers, which could be similar to our study due to the location of the rhabdomyosarcoma selected cases." (PMID 40710368, 2025).
iron deficiency (2 papers, 2026). "Although preclinical studies suggest a role for FGL1 in iron metabolism, its clinical behavior in human iron deficiency anemia (IDA) remains unclear." (PMID 41867684, 2026). "By calibrating hepcidin through SOCS3-, FGL1-, and HIF2α-mediated control of IL-6-STAT3 and BMP-SMAD, RYGB mitigates the risk of profound iron deficiency while preserving beneficial macrophage and metabolic adaptations." (PMID 41598416, 2026).
kidney transplant (2 papers, 2021 to 2022). A surgical procedure in which one or both kidneys from a donor are implanted into a recipient. "Comprehensive sample analysis revealed dysregulation of FGL1/LAG‐3 and PD‐L1/PD‐1 immune checkpoints in allogeneic heart transplantation mice and clinical kidney transplant patients." (PMID 34738731, 2022).
Lewis lung carcinoma (2 papers, 2022 to 2025). "Further experiments confirmed that FGL1 KD prevented the proliferation of Lewis lung carcinoma cells both in vitro and in vivo (P < 0.05)." (PMID 36268014, 2022). "Stable Lewis lung carcinoma (LLC) and H226 cell lines with low FGL1 knockdown were constructed using lentivirus vectors." (PMID 41024301, 2025).
metastatic cancer (2 papers, 2021). A carcinoma which has spread from the original site of growth to another anatomic site. "Although the number of ongoing clinical trials targeting FGL1 are not sufficient, a significant positive correlation between FGL1 expression and long-term prognosis has been observed for patients with multiple types of metastatic cancer who are treated with anti-PD-1/PD-L1 therapy." (PMID 34526102, 2021).
metastatic tumor (2 papers, 2023 to 2024). "Upregulation of OTU deubiquitinase 1 (OTUD1) stabilizes FGL1 through deubiquitination, further influencing the immune escape of metastatic tumors via the FGL1-LAG-3 axis." (PMID 38816776, 2024). "We speculate that the abnormal upregulation of FGL1 in liver metastatic tumors is closely related to the liver microenvironment." (PMID 37872170, 2023). "However, knockdown of either OTUD1 or FGL1 in MC38 cells reduced hepatic metastases, which could be rescued by overexpressing rFGL1, indicating the critical role of FGL1 in TNFα-mediated progression of metastatic tumors." (PMID 37872170, 2023). "Nevertheless, the potential role of FGL1 in the immune escape of metastatic tumors in the liver microenvironment has not been investigated, and its regulation remains unclear." (PMID 37872170, 2023).
preeclampsia (2 papers, 2021 to 2023). Preeclampsia is a hypertensive disorder of pregnancy that is characterized by new-onset hypertension with proteinuria presenting after 20 weeks of gestation, and depending on mild or severe forms may initially present with severe headache, visual disturbances, and hyperreflexia. "Fibrinogen-like 1 (FGL1) is involved in liver injury and liver regeneration, but its role in placenta and preeclampsia (PE) remains unclear." (PMID 34957095, 2021).